CXCR4 (C-X-C motif chemokine receptor 4)
Diseases named in the same sentence as CXCR4 in open-access papers (continued):
Sharing a sentence is not in itself a finding about the gene and the disease.
tumor (continued). "Throughout brain development, microglia regulate a number of immune chemokines, such as CXCL12 and CXCR4, which could create a specific microenvironment for tumor cells to emerge." (PMID 37509316, 2023). "Finally, through clinical specimens and in vitro studies of GBM patients, we found that CXCR4 was significantly overexpressed in GBM tissues and was closely associated with tumor inflammatory responses." (PMID 37626511, 2023). "SDF1α/CXCR4 axis plays a role in tumor progression with the proposed mechanism that the binding of SDF-1α to its GPCR CXCR4 activates the downstream MAPK, PI3K pathways, which lead to cell proliferation, survival, chemotaxis, and transcription of gene expression." (PMID 37280713, 2023). "This aggressive brain cancer tumor promotes proliferation by CXCR4/SDF 1 alpha chemokines." (PMID 38004925, 2023). "Moreover, scRNA-seq can identify heterogeneity in the tumor population and help identify specific cell subgroups, including stem-cell-like cells expressing CXCR4." (PMID 37679408, 2023). "Moreover, since the CXCL12/CXCR4 oncogenic bridge serves as communication between tumor cells and stromal cells, numerous molecules targeting CXCL12/CXCR4 signaling have been developed to interfere with tumor growth." (PMID 36980182, 2023). "Staining for integrin and chemokine (C-X3-C motif) receptor (CXCR4; a tumor proliferation and invasion marker) also revealed that the LOC could support MDA-MB-231 cell attachment and migration inside the scaffold." (PMID 37771785, 2023). "Additionally, co-expressing the chemokine receptor CXCR4 in the CAR-NK cells for improved tumor-homing enhanced the anti-tumor effect." (PMID 36768432, 2023). "Given the impact of CXCR4 signaling on both tumor behavior and the immune system, its modulation may have cancer therapeutic implications." (PMID 37280713, 2023). "The C-X-C chemokine receptor type 4 (CXCR4), a conserved seven-transmembrane structure spanning the G-protein-coupled receptor, was identified as contributing to tumor metastasis in response to its endogenous ligand stromal cell-derived factor 1 (SDF-1, also named CXCL12)." (PMID 37047831, 2023). "It has been reported that high CXCL12 levels in GBM may attract CXCR4-positive vascular and inflammatory cells such as TAMs that, once within the tumor, secrete tumor-promoting cytokines as well as growth and pro-angiogenic factors." (PMID 37190507, 2023). "The correlation of CXCR4 with immune infiltration and tumor was analyzed using CancerSEA and TIMER." (PMID 37626511, 2023). "CSC marker gene CXCR4 may be a key gene facilitating malignant phenotypes of CSCs, which thus promotes tumor growth and liver metastasis of GC." (PMID 37679408, 2023). "Notably, the interruption of the SDF-1/CXCR4 signaling axis via CXCR4 antagonists diminishes the tumor cells’ migratory and invasive prowess, underscoring the axis’s centrality in PDAC progression." (PMID 37958483, 2023). "The CXCR4 expression was significantly higher (P-value = 0.022) in the stroma of tumor tissues than in the stroma of non-tumor tissues (23.5 ± 6.1 and 8.7 ± 4.6, respectively), whereas no statistical association was possible in the evaluation of expression in tissues globally or in immune cells." (PMID 37697316, 2023). "NOTCH2NL, MYBL2, and UBE2T were reported to be involved in tumorigenesis, while CXCR4 and IL18R1 were associated with immune response and pathway activation, indicating SRSF1 may take part in MM progression via tumor-related pathways." (PMID 37206090, 2023). "CXCR4 is expressed not only on BM progenitor cells but also on various types of tumor cells." (PMID 37679605, 2023). "SDF‐1/CXCR4 has an important role in a variety of biological processes such as immunity, inflammation, embryonic development, and organogenesis, as well as in tumor growth or metastasis, HIV disease, and WHIM (warts, hypogammaglobulinemia, infections, and myelokathexis) syndrome." (PMID 37614198, 2023).
tumor (continued). "Thus, a combination treatment targeting carcinoma associated fibroblasts (CAF) by CXCR4 blockade and immune cells by ICI, increased T cell migration and activation towards tumor cells was observed resulting in tumor cell apoptosis." (PMID 37638045, 2023). "Notably, CXCR4 is overexpressed by many different types of cancers, where it plays a role in tumor metastasis, and also a critical role in mobilizing and recruiting MDSC from bone marrow." (PMID 37114134, 2023). "Finally, the MMP SDF1α/CXCR4 signaling pathway inhibits tumor cell metastasis and invasion, induces autophagy, and affects tumor metabolic reprogramming, resulting in anti-tumor effects." (PMID 37761088, 2023). "Similarly, the CXCR4 signaling pathway is involved in tumor invasion and metastasis in CRC, the estimated third-leading cause of cancer death." (PMID 37372958, 2023). "Moreover, it has been reported that several chemokine receptors, such as CCR2 and CXCR4, are expressed on the surface of MSCs, and they are critically involved in the homing potential of MSCs toward tumor tissues." (PMID 36831094, 2023). "The results of tumor growth and weight measurement showed that compared to the sh-NC group, the tumor growth rate in the sh-CXCR4 group of nude mice was significantly reduced, and the tumor weight and volume were significantly smaller, with a significant increase in nude mice weight." (PMID 37679408, 2023). "In addition, CAR-NK cells engineered to express CXCR1 or CXCR4 also experienced enhanced trafficking to the tumor." (PMID 37205115, 2023). "CXCL12/CXCR4 signal transduction not only promotes dysplasia and stress of tumour tissues, inducing physical barrier for therapeutic agents and T cell penetration, but also functions importantly to promote tumour cell migration, proliferation and invasions." (PMID 37162544, 2023). "Previous data indicate that the inhibition of epithelial or stromal SDC2 with SDC2 peptides retards breast tumor growth and metastasis, as well as retraining tumor evasion (via downregulation of TGFβ-regulated programmed death ligand 1 and CXCR4) in a xenograft mouse model." (PMID 36980680, 2023). "Recruitment of monocytes is one of the many tumor-promoting effects exerted by CXCR4." (PMID 37153567, 2023). "Anti-CXCR4 treatment-induced vascular normalization and reduced hypoxia could reprogram the tumor immune microenvironment and synergize with the direct effects of AMD3100 on immunosuppressive myeloid and regulatory T cells." (PMID 36831366, 2023). "CXCR4 is overexpressed in metastatic tumor tissues in PCa patients, and the metastatic growth correlates with higher levels of CXCR4 expression in primary tumor specimens." (PMID 36831366, 2023). "Likewise, in vivo treatment with CXCR4 antagonists reduced intratibial growth and tumor-induced osteolysis of PC3 cells, whereas overexpression of CXCR4 increased PC3 tumor growth in bone and osteolysis." (PMID 37025604, 2023). "The use of NP that overexpress CXCR4 facilitate the homing in injured tissues or tumor sites." (PMID 38004925, 2023). "In addition, macrophage migration inhibitory factor (MIF) is secreted to bind to CXCR4 on tumor cells to activate the Akt pathway to promote angiogenesis." (PMID 37700840, 2023). "CXCR4 signaling contributes to cancer metastasis and suppresses anti-tumor immunity." (PMID 37280713, 2023). "CXCR4 is overexpressed in a variety of malignancies, including breast, pancreas, thyroid, prostate, kidney, lung, and brain cancers, contributing to tumor growth, angiogenesis, tumor microenvironment interactions, metastasis, and therapeutic resistance." (PMID 37749552, 2023). "Additionally, anti-VEGFR2 monoclonal antibody (DC101) and the antagonist of the SDF1 receptor CXCR4 (AMD3100) have also shown significant reduction in microvessel density in CSC-high tumor-bearing mice." (PMID 37784157, 2023).
tumor (continued). "In addition, the population of circulating tumor cells in PCa following radiotherapy was apparently more stable with the expression of CXCR4." (PMID 37576552, 2023). "CXCR4 is present on both the neovasculature and the tumour cells." (PMID 36140541, 2022). "The targets PD-L1 and CXCR4 are expressed in various cancers and tumour microenvironments." (PMID 36284271, 2022). "Thus, connecting CXCR4 with HSCs and blocking the CXCL12-CXCR4 axis can make tumor cells sensitive to chemotherapy drugs." (PMID 36569863, 2022). "Notably, CXCR4 expression in tumor cells and vasculogenesis in the TME were decreased following DPN treatment, further featuring an MCL tumor cell–TME connection." (PMID 35804870, 2022). "When high CXCR4 expression is present, targeted imaging with [68Ga]Ga-Pentixafor might complement tumor imaging while targeted radionuclide therapy could be possible using [177Lu]Lu-Pentixather." (PMID 33550492, 2022). "Interestingly, strong cytoplasmic CXCR4 staining was more frequent among samples derived from metastases compared to primary tumours and local recurrences." (PMID 36140541, 2022). "Since the SDF-1/CXCR4 axis plays a crucial role in recruiting immune cells such as MDSCs and Tregs to the tumor microenvironment, we speculate that upregulation of SDF-1 expression may induce chemoresistance in TNBC via infiltration of immune cells." (PMID 36341391, 2022). "Moreover, MM cells recruit tumor-supporting macrophages by the CXCR4/CXCL12 axis and drive their polarization towards the M2 phenotype." (PMID 35958625, 2022). "Similarly, lower expression of CXCR4/CXCR7 and CXCL12 is associated with increased tumor size, local invasion, poor differentiation, advanced lymph node stage, advanced tumor stage, and lymphovascular invasion." (PMID 35406582, 2022). "More recently, it has been shown that CXCR4 is also upregulated in cancer stem cells (CSCs), or tumor-initiating cells, a population of malignant cells within a tumor able to self-renew and differentiate to produce the heterogeneous lineages of cancer cells that constitute the tumor." (PMID 36293358, 2022). "Therefore, inhibition of the CXCR4 axis should slow tumour progression and metastasis and improve the chemosensitivity of tumours." (PMID 36140541, 2022). "Clinically, manipulation of CXCL12/CXCR4 axis-mediated responses may contribute to the inhibition of CAF infiltration in ESCC tumor mass." (PMID 35941662, 2022). "SOX11 also regulates CXCR4 expression, with CXCR4 being important for the tumor–TME interaction." (PMID 35804870, 2022). "However, interobserver analysis showed good agreement for the scoring of CXCR4 expression of tumor cell staining." (PMID 33550492, 2022). "Indeed, in many organs, including breast, ovary, prostate, lung, kidney, as well as within the gastrointestinal tract, tumor progression is likewise affected by CXCR4, CXCR3, and CXCR7." (PMID 36539774, 2022). "For instance, a decrease in radiotracer accumulation in normal organs in patients with high tumor burden has been reported for theranostic targets other than CXCR4, e.g., for somatostatin receptor (SSTR) and prostate specific membrane antigen (PSMA)-targeting radiotracers." (PMID 35312939, 2022). "Membrane expression of this receptor drives CXCR4-dependent metastatic progression in other tumor types, while its role was still unknown in EC." (PMID 35884987, 2022). "Furthermore, co-treatment of AMD3100 (a CXCR4 inhibitor) and docetaxel significantly reduces tumor growth in the PC-3 CRPC xenograft mouse model relative to monotherapy and can sensitize PC-3 cells to docetaxel." (PMID 36671452, 2022). "In addition, CXCR4/FOXP3 double staining in Treg was carried out to confirm the TIL balance in the tumor microenvironment." (PMID 35358193, 2022). "Furthermore, the CXCR4 expressed on the surface of cancer cells attracts CAFs to the tumour environment, which in turn attracts CXCR4-positive bone marrow-derived progenitor cells and participates in angiogenesis." (PMID 36284271, 2022).
tumor (continued). "Additionally, CXCL12 can act on tumor cells via CXCR4, promoting tumor cell proliferation and dissemination." (PMID 36612058, 2022). "Inhibition of the CXCL12/CXCR4 axis through the CXCR4 inhibitor plerixafor could abrogate the initial establishment of tumor growth in vivo." (PMID 36254250, 2022). "IGS can be then envisaged as a survey process that exposes tumor tissues to immunosurveillance: in a small percentage of cases, this event leads to tumor rejection and antitumor immunity; in a large percentage, instead, the tumor-promoting activity of the CXCL12/CXCR4 axis prevails." (PMID 36293358, 2022). "Therefore, it is possible to theorize that patients with higher expression of CXCR4 on CAMLs (i.e. hematopoietic myeloid cell) would have more CAMLs found in circulation based on CXCR4 involvement in recruiting myeloid cells to the tumor site." (PMID 35259193, 2022). "Besides, inhibiting CXCR4 combined with anti-angiogenesis drugs improved the anti-tumor efficacy via the ERK pathway in liver cancer." (PMID 35585567, 2022). "The interacting of CXCL12 and CXCR4 could activate divergent intracellular pathways related to chemotaxis, cell proliferation and gene transcription in tumor development." (PMID 36387901, 2022). "The mechanism may be related to the down-regulation of the CXCR4/CXCL12 signaling pathway in tumor tissues." (PMID 35814470, 2022). "• High CXCR4 tumor expression in recurrent HGSOC biopsies might be indicative for sensitivity to chemotherapy." (PMID 35397601, 2022). "Inversely, CXCR4 expression significantly correlates with the tumor primary site." (PMID 36816176, 2022). "CXCR4 also presented as a key driver in tumor progression in HeyA8 xenograft model." (PMID 35698138, 2022). "CD184 (CXCR4) is a G-protein coupled receptor discovered on the surface of metastatic tumor cells." (PMID 35311145, 2022). "Notably, ligand/receptor pairs such as Il33/Il1rl1 (St2) and Cxcl12/Cxcr4 not only were abundant in tumors but also detected in cultured tumor cells." (PMID 35902768, 2022). "In this context, the CXCL12/CXCR4 axis plays a decisive role in the development and progression of cancer, including cell proliferation and metastasis, tumor angiogenesis, the epithelial mesenchymal transition, intracellular calcium increase, and gene transcription." (PMID 35893797, 2022). "In tumor growth, CXCR4 is a major contributor to the recruitment of MDSCs." (PMID 36358977, 2022). "CXCR4 expression was reported in 53/76 (69.7%) of tumor-infiltrating cells." (PMID 36359736, 2022). "This poor prognosis may correlate with the metastatic process, and tumor stage that significantly higher CXCR4 expression." (PMID 36816176, 2022). "Therefore, the role of CXCR4 in EC is still controversial regarding its possible effect on tumor growth or metastatic dissemination." (PMID 35884987, 2022). "Finally, to explore the involvement of MMP9 in angiogenic and invasive processes, we concomitantly analyzed the baseline plasma expression of five related factors implicated in the tumor microenvironment: MMP2, VEGFA, VEGFR2, CXCR4, and CXCL12." (PMID 34980260, 2022). "Thirdly, knockdown of RON could suppress tumor formation and result in the lower expression of CXCR4 in nude mice tumorigenesis." (PMID 36103228, 2022). "So, it is to be confirmed whether CXCR4 signaling is a tumor microenvironmental factor inducing radiotherapy resistance." (PMID 35993091, 2022). "CXCR4 plays relevant roles also in the tumorigenic process by directly acting at multiple steps; it is, in fact, overexpressed in many tumor cells affecting growth and invasion, suggesting that CXCR4 is a driver of human malignancies and a marker of poor prognosis." (PMID 36293358, 2022). "In the CD8-negative cohort, the combined high expression of CXCR4 and its ligand SDF-1 was associated with decreased overall survival, suggesting that the detrimental effect of CXCR4/SDF-1 depends on the density of tumor infiltrating CD8-positive T lymphocytes." (PMID 36419107, 2022).
tumor (continued). "Thus, 60% of the total emitted fluorescence, out of the total administered dose, is registered in tumor tissue, indicating its CXCR4-dependent internalization." (PMID 35884987, 2022). "Furthermore, CAF-secreted CXCL12 recruits more CXCR4 expressing cells, like endothelial cells, epithelial cells and immune cells to activate intracellular pathways leading to cell proliferation and tumor progression." (PMID 35565443, 2022). "CXCL12/CXCR4 chemokine axis participates in tumor progression and metastasis." (PMID 35395810, 2022). "The CXCL12 and CXCR4 tumor expression positively correlated (Spearman’s r = 0.42, p = 0.004)." (PMID 36359736, 2022). "Some studies reported that CXCR4 might modulate tumor cells to metastasize to a specific organ as it controls angiogenesis." (PMID 36816176, 2022). "Although blocking CXCR4 reduces fibrosis and increases T cell infiltration in some desmoplastic tumor types, in highly vascular HCC after relapse from AAT, blocking CXCR4 alleviated immunosuppressive cell recruitment and angiogenesis resistance mechanisms to some extent." (PMID 35712656, 2022). "Here, we generated a new CXCR4-overexpressing (CXCR4+) orthotopic EC mouse model, using a novel surgical procedure, and set up a highly sensitive immunohistochemical tumor cell marker to detect small metastatic foci and single cancer cells in clinically relevant organs." (PMID 35884987, 2022). "Therefore we investigated the role of pCXCR4 and CXCR4 expression of the tumor cells and of tumor infiltrating immune cells (TIC) in high-grade serous OC and their association with the recurrence-free (RFS) and overall survival (OS)." (PMID 35397601, 2022). "The CXCL12/CXCR4 pathway is also implicated in the activation of CD44+/CD133+ prostate progenitor population, a drug-resistant population of cells that lead to tumor relapse and affects differentiation potential, cell adhesion, clonal growth and tumorigenicity of PCa cells." (PMID 35406450, 2022). "C‐X‐C‐motif chemokine receptor 4 (CXCR4) is a G‐protein‐coupled receptor involved in a number of physiological processes in the hematopoietic and immune systems and also has important roles in promoting tumor cell proliferation, metastasis, and angiogenesis." (PMID 36254250, 2022). "Moreover, when CXCR4+ AN3CA cells were inoculated, all primary tumor and metastasis maintained the high CXCR4 membrane expression observed in culture." (PMID 35884987, 2022). "In addition, relative to PSMA or SSTR which are overexpressed on the tumor cell surface, CXCR4 is a dynamic receptor expressed mainly in the tumor microenvironment." (PMID 35312939, 2022). "In particular, after a short recapitulation of background information, we will discuss the activities of CXCR4 and CXCL12 in the tumor microenvironment and the ability of CXCR4 to interact laterally with other receptors and to modulate processes that can be exploited in the context of immunotherapy." (PMID 35565443, 2022). "Certainly, for its formation and progression, GBM cells engage different chemokines such as CXCL8, CXCL16, CX3CL, CCL5, CXCL12, and their receptors CXCR1-2, CXCR6, CX3CR1, CCR5, CXCR4-7, respectively, for a chemokine network communication mechanism to maintain and increase the tumor malignancy." (PMID 35745762, 2022). "Moreover, the detrimental effect of CXCL12/CXCR4 is found to depend on the density of tumor-infiltrating CD8-positive T lymphocytes." (PMID 36612163, 2022). "Both CXCR4 and human vimentin IHC staining were performed in consecutive primary tumor slides." (PMID 35456719, 2022). "Moreover, CXCR4 overexpression has also been related to higher tumor grade, lymph node metastasis, and poor overall survival." (PMID 35456719, 2022). "Moreover, we have also developed a CXCR4+ subcutaneous (SC) model which we next used to demonstrate that the protein-based T22-GFP-H6 nanocarrier that targets CXCR4+ cells, displays a high selectivity in its accumulation in CXCR4+ EC tumor tissues." (PMID 35884987, 2022).